BRCA1 (BRCA1 DNA repair associated)
Diseases named in the same sentence as BRCA1 in open-access papers (continued):
Sharing a sentence is not in itself a finding about the gene and the disease.
cancer (continued). "In addition, the data regarding the cancer risks in relatives of BRCA1/2 carriers are largely based on Western populations; scant data exists that pertains to Chinese populations." (PMID 36861435, 2023). "One of these is a small sub-clonal cancer call that, after beginning treatment, develops into the primary clone that does not react to targeted therapy and does not carry the BRCA1/2 mutation." (PMID 38174205, 2023). "Therefore, the aim of the current study is to investigate the relationship between coping self-efficacy and psychological morbidity in cancer-unaffected BRCA1/2 PV carriers." (PMID 36767056, 2023). "Several characteristics, such as expression signatures, DNA mismatch repair deficiency (MMR-D), and BRCA1 status, are currently used agnostically regardless of cancer origin." (PMID 37965470, 2023). "Many cancers arising in females with a BRCA1/2 PV can be prevented." (PMID 37887578, 2023). "When homologous recombination repair genes BRCA1/2, ATM, PALB2, and CHEK2 are inactive, a variety of error-prone and non-conservative DNA repair pathways are used, increasing the incidence of cancer and worsening its prognosis while also causing genomic instability." (PMID 37732318, 2023). "Ultimately, gaining a deeper understanding of BRCA1’s role as a transcriptional regulator may pave the way for improved cancer treatments and better outcomes for patients with BRCA1-related malignancies." (PMID 37762577, 2023). "Furthermore, the deletion of BRCA1 in human fibroblasts significantly increased the uptake of cancer EVs compared to wild-type fibroblasts, suggesting that this specific genomic alteration has an impact on their biological characteristics." (PMID 37371036, 2023). "The case report suggested that homozygous BRCA1 c.2800delAA mutation did not increase cancer risk beyond heterozygosity." (PMID 38146508, 2023). "In recent retrospective studies, BRCA1/2 germline mutations were associated with significantly worse outcomes after definitive local therapy for PCa with a median cancer-specific survival of 8.6 years compared to 15.7 years in non-carriers (p < 0.01)." (PMID 38178943, 2023). "Furthermore, correlation analysis of cancer cell lines from Cancer Cell Line Encyclopedia (CCLE) data showed that LSD1 mRNA expression was positively correlated with BRCA1/2, and RAD51 mRNA expression." (PMID 37973845, 2023). "However, several studies have reported that women with a family history of cancer or with BRCA1/2-positive had higher levels of psychological stress than their counterparts." (PMID 38115125, 2023). "Among cancer predisposition genes, most direct-to-consumer (DTC) genetic tests evaluate three Ashkenazi Jewish (AJ) founder mutations in BRCA1/2, which represent a small proportion of pathogenic or likely pathogenic variants (PLPV) in cancer predisposing genes." (PMID 37535880, 2023). "For example, PARP1 promotes the repair of ssDNA breaks, which, unless repaired, can become DSBs, and PARP inhibitors therefore selectively target cancer cells with defective DSB repair ability and have thus been used to treat breast cancer patients carrying BRCA1 or 2 mutations." (PMID 37009801, 2023). "Patient #10, a woman with uterus carcinosarcoma with lung metastasis without a family history of cancer, was a heterozygous carrier of the pathogenic variant BRCA1 c.3331_3334del; p.Gln1111Asnfs*5, associated with hereditary breast and ovarian cancer syndrome." (PMID 36550207, 2023). "For example, germline BRCA1/2 variants are not only associated with increasing risk for serous/serous-like EC, but they also confer sensitivity to PARP inhibitors, which have been widely approved in other cancer types." (PMID 37730563, 2023). "The identification of novel DNA damage vulnerabilities could lead to the use of PARP inhibitors in the treatment of BRCA1-proficient cancers and provide new therapeutic avenues to overcome PARP inhibitor resistance." (PMID 38201233, 2023).
cancer (continued). "Therefore, this is the first study reporting the frequency and spectrum of germline SNV/indel and CNVs in BRCA1/2 among the Tanzanian BC patients unselected for family history of cancer and age at diagnosis." (PMID 35908255, 2023). "By deciphering the complex interplay between BRCA1 and its transcriptional co-regulators, we may uncover critical pathways that drive tumorigenesis and identify potential vulnerabilities in cancer cells." (PMID 37762577, 2023). "Because cells with BRCA1 defects display reduced fork protection, CtIP may prove to be an effective target to enhance genotoxic cancer therapies in BRCA1-mutant cancers." (PMID 38069223, 2023). "Since the patients under study are long-time survivors, they undertake a different decision-making pathway from those who are prescribed BRCA1/2 genetic testing at the time of cancer diagnosis, for whom the test may also have predictive significance." (PMID 37723374, 2023). "For non-AJ individuals, limiting evaluation to the AJ founder BRCA1/2 mutations missed >90% of mutations in actionable cancer risk genes." (PMID 37535880, 2023). "Intratumoral heterogeneity of chemonaive BRCA1-driven cancers has been shown in several studies." (PMID 36768191, 2023). "While reported safe for cancer patients, there are limited studies addressing the safety profile and outcomes of COVID-19 vaccination among individuals with germline PV/LPV in cancer predisposition genes such as BRCA1/2." (PMID 37046302, 2023). "Previous research has shown that many human cancers exhibit BRCA-like mutational signature without harboring any BRCA1, BRCA2, or PALB2 mutations." (PMID 37032811, 2023). "Cancer cell lines and tumours harbouring mutations in exon 11 of BRCA1 express a BRCA1-Δ11q splice variant lacking the majority of exon 11 but retains partial BRCA activity, mediating PARPi resistance." (PMID 37430137, 2023). "We hypothesized that BRCA1 tumors have score 4 elasticity (no strain in the entire lesion) rather than scores 1, 2, 3, or 5 because TN subtype (which is common in BRCA1 cancers) tumors are likely to have well-circumscribed margins." (PMID 36905492, 2023). "There is no clear evidence explaining the predisposition to cancer in male BRCA2 mutations carriers compared to BRCA1 mutation carriers." (PMID 38203374, 2023). "Mutations in BRCA1, BRCA2 or PALB2 work synergistically with PARPi to cause cancer cell death." (PMID 37190285, 2023). "In addition, we demonstrate that only 0.5% of all individuals referred for clinical genetic testing were found to have a BRCA1/2 AJ founder variant, while 8.5% had a PLPV in one of 41 actionable cancer risk genes." (PMID 37535880, 2023). "They performed global transcriptional and metabolite profiling of a BRCA1-mutated BC cell line with or without transfection with wild-type BRCA1 in order to obtain a comprehensive view of the participation of BRCA1 in cancer cell metabolism." (PMID 37109525, 2023). "The average cumulative lifetime risk of women without a history of cancer (previvors) is about 70% for BC and 44% (BRCA1 variant) or 17% (BRCA2 variant) for OC." (PMID 37845719, 2023). "BRCA1 also controls cancer metabolism by ubiquitination of AKT, eventually suppressing oncogenesis." (PMID 37176148, 2023). "Notably, even in BRCA1 and BRCA2 gene mutation carriers, subsequent somatic genetic events must occur to transform a normal cell into a cancer cell that can also result in therapeutic vulnerabilities." (PMID 35703177, 2022). "Germline mutations in the BRCA1 and BRCA2 genes are well-known mechanisms of HRD, and loss of BRCA1 or BRCA2 thus poses a significant risk to genome integrity, leading not only to cancer predisposition, but also affecting the sensitivity to DNA-damaging agents and thus therapeutic approaches." (PMID 35785170, 2022).
cancer (continued). "A three‐drug combination consisting of pyridostatin, NU‐7441 and paclitaxel can effectively suppress growth or even eradicate BRCA1‐ or BRCA2‐deficient tumours and we propose that this triple combination represents an effective therapeutic strategy against BRCA‐mutated cancers." (PMID 35107878, 2022). "Additionally, clinical trials have shown promise in treatment of BRCA1/2 PV carriers in other cancers." (PMID 36497436, 2022). "As several BRCA1-related breast cancers are associated with activation of PI3K signaling, dual inhibitors targeting PARP and PI3K can be a promising strategy for cancer treatment." (PMID 35955544, 2022). "Of note, remarkable studies in 2005 demonstrated that PARP inhibition selectively kills the BRCA1/2 mutant tumor cells, leading to the rapid clinical development of PARP inhibitors (PARPi) for patients with homologous recombination (HR)-deficient cancer." (PMID 36284291, 2022). "The characteristics of BRCA1 LGR across multiple cancers are summarized." (PMID 36147908, 2022). "Cancer cells with BRCA1/2 protein deficiency or lacking functional mutations are more sensitive to PARPis than normal cells." (PMID 36139634, 2022). "Indeed, BRCA1 mutations, as well as mutations in other HRR genes, predispose genomic instability and trigger cancer formation." (PMID 36231059, 2022). "Then, high cancer worry was present in 38% and 36% of the BRCA1/2-PV carriers respectively." (PMID 34997316, 2022). "Cancer with defected BRCAness shared many features such as the cancer with defected BRCA1/2." (PMID 36497135, 2022). "While the FL- BARD1, either individually or in complex with BRCA1, was reported to display a tumor suppressor function, BARD1 isoforms such as BARD1β and δ have an antagonistic effect on full-length BARD1, leading to cancer susceptibility and oncogenicity." (PMID 35650591, 2022). "PKM2 deletion in the mammary glands of a BRCA1-loss-driven cancer model did not postpone carcinogenesis." (PMID 36193432, 2022). "BRCA1/2 carriers with different genotypes have significantly different cancer risks." (PMID 35378767, 2022). "Thus far, data on cancer worry in BRCA1/2-PV carriers are very limited, especially regarding the course of cancer worry over time." (PMID 34997316, 2022). "In addition to its genomic and cancer-related activities, more recent evidence revealed that BRCA1 displays a number of metabolic and hormone-like types of action." (PMID 35432218, 2022). "In addition, LOH is particularly relevant in inherited cancer predisposition syndromes, which present germline mutations in tumor suppressors such as BRCA1 and BRCA2 and play a crucial role in increasing the cancer risk." (PMID 35682766, 2022). "BRCA1 variants were more frequent in patients presenting a positive family history of any cancer compared with the patients who did not have a positive family history of any cancer (7.5% vs. 2.7%, p = 0.003)." (PMID 36232564, 2022). "The cumulative risk of cancer to age 85 years was estimated for carriers and noncarriers of pathogenic variants in BRCA1 and/or BRCA2 for the 7 significantly associated cancer types." (PMID 35420638, 2022). "However, a subset of these BRCA1/2-PV carriers has persisting major cancer concerns up to 1 year after surgery." (PMID 34997316, 2022). "Therefore, there is an urgent clinical need for tools to predict the frequency of BRCA1/2 deleterious variants in Asian BBC patients balancing the increased demand for and cost of cancer genetics services." (PMID 36324133, 2022). "The function of breast cancer type 1 (BRCA1) is regulated by PARylation." (PMID 36077221, 2022).
cancer (continued). "How BRCA1 mutation-caused genome instability develops from the non-transformed cells to the transformed cancer cells remains largely elusive." (PMID 35869059, 2022). "Lack of family history does not imply significantly lower cancer risks, and lifetime risk of developing cancer was 83%, 76% for BRCA1, BRCA2 carriers identified by screening, respectively, not significantly different than risks to carriers with family history." (PMID 36551598, 2022). "This emphasizes the differences in transmission modalities awareness across genders within first-degree relatives, leading to the well-known disparity in terms of knowledge of the BRCA1/2-related cancer risks between men and women, and consequently confirming family history as not influent." (PMID 35303741, 2022). "Our results indicate that combining functional assay with other forms of data regarding BRCA1 and BRCA2 missense variants can overcome this limitation and lead to a more accurate determination of whether a variant results in increased cancer risk." (PMID 35665744, 2022). "In addition, the BRCA1 p.His1686 amino acid position is involved in several residue changes previously associated to BC and BRCA-related cancers." (PMID 36741700, 2022). "While this is sometimes achieved via compensatory mechanisms, such as increased activity of RAD52, studies have also demonstrated secondary somatic reversion of mutated genes in the DDR pathway, such as in BRCA1/2 and RAD51 genes, which can restore their function in cancer cells." (PMID 35626165, 2022). "Neither personal history of a cancer diagnosis nor having undergone risk-reducing surgery differed according to the genetic variant (i.e., BRCA1 vs. BRCA2)." (PMID 35326645, 2022). "Similar to the BRCA1/2 literature, individuals with a PV reported higher levels of testing-related concerns and cancer-specific distress, as well as higher uptake of prophylactic surgery in both affected and unaffected individuals compared to those with VUS or negative result." (PMID 35733200, 2022). "The results from the first three PDXs in the series suggest that loss of BRCA1 methylation can occur shortly after a single exposure to chemotherapy in the patient, and that the resultant cancers progressively increase BRCA1 expression after successive chemotherapeutic exposures." (PMID 35857626, 2022). "We aimed to understand the decision-making process related to the willingness to undergo BRCA1/2 genetic testing, risk-reducing salpingo-oophorectomy (RRSO), or risk-reducing mastectomy (RRM) among the general public, cancer patients, and healthcare professionals in South Korea." (PMID 35629239, 2022). "Notably, seven genes associated across more than one cancer type, of which three (BRCA1, EP300, MTOR) associated with the same somatic mutational component across two different cancer types." (PMID 35764656, 2022). "Altogether, these findings suggest an intriguing working model in which loss of Brca1 in cancer cells results in upregulation of S100A9, which, in turn, not only positively regulates S100A9 expression in cancer cells but also acts extracellularly to induce MDSC accumulation." (PMID 35304461, 2022). "Role of BRCA1 in DNA damage response, kinetochore metaphase signaling, cell cycle control of chromosomal replication and superpathway of cholesterol biosynthesis were among the top pathways presented in most of the cancer types." (PMID 36046053, 2022). "We pursued a two-stage approach: first, all patients were screened for PVs in BRCA1/2; second, BRCA1/2-negative patients were further analyzed for PVs in non-BRCA1/2 cancer predisposition genes." (PMID 35805063, 2022). "Some studies seem to suggest the presence of an increased perception of cancer risk in healthy men tested for BRCA1/2 (i.e., with no previous cancer diagnosis), irrespective of the genetic test result." (PMID 35448177, 2022).
cancer (continued). "The use of PDX models of BRCA1meth TNBC was experimentally important in that, to our knowledge, there is no established cancer cell line with methylation of both BRCA1 promoter alleles." (PMID 35857626, 2022). "In a retrospective study, biallelic BRCA1/2 alteration was associated with increased LoH across multiple cancer types, including biliary tract cancers (BTC), although the magnitude of this association was variable across each cancer type." (PMID 35626165, 2022). "Notably, REV1- Polζ was recently identified to have a protective and mutagenic role in BRCA1/2 mutant cancer cells by filling in PRIMPOL-dependent ssDNA gaps that arise in these cells upon replication fork stalling at SMUG1-mediated DNA lesions." (PMID 36075897, 2022). "One of the main objectives of this study was also to detect BRCA1 mutations in CTCs and not in plasma, to directly compare mutations in cancer cells and PARP expression." (PMID 35406503, 2022). "This may be important since BRCA1/2 mutant cancer cells can also develop resistance against PARP-inhibitors highlighting the need for novel therapeutic approaches to prevent or overcome resistance." (PMID 35869047, 2022). "Talazoparib inhibits PARP1 and PARP2, two key enzymes involved in DDR, and effectively traps PARP on single-stranded DNA breaks, causing an accumulation of double-stranded DNA breaks that cannot be effectively repaired in cancer cells with mutations in DDR/HRR genes, including BRCA1/2." (PMID 35907135, 2022). "Few studies evaluating OS and BRCA1/2m for other cancer types were found." (PMID 35909902, 2022). "We previously reported evidence for cell-nonautonomous mechanisms of cancer predisposition in humans and experimental animals carrying germline BRCA1 or Brca1 mutations." (PMID 35701800, 2022). "The landscape of somatic mutations in BRCA1/2-associated PDAC is essentially indistinguishable from that of sporadic cancers." (PMID 35805011, 2022). "Family history of BRCA1/2 related cancers and mutations should be investigated not only in terms of knowledge of relatives’ BRCA-related cancer diagnoses but also in terms of health literacy on this matter among families." (PMID 35303741, 2022). "In addition, we discuss the roles of iNOS, HER2, BRCA1/2, and NO metabolism in the pathophysiology of cancer stem cells." (PMID 35740092, 2022). "Since 53BP1 expression is frequently lost in BRCA1/2-mutated or triple-negative breast cancers, it is thought that 53BP1 could be used as a biomarker for predicting the response of BRCA-mutated cancers to PARP inhibitor therapy." (PMID 35955544, 2022). "Since, we found that all patients with BRCA2 mutant cancers in the COH cohort achieved pCR, and all our subsequent analyses also showed improved outcomes in BRCA2 mutant cancers, we grouped TNBCs harboring BRCA1 and BRCA2 pathogenic mutations together as BRCAmut cancers." (PMID 35857626, 2022). "Germline biallelic pathogenic variants (PVs) in BRCA1 or BRCA2 result in different forms of Fanconi Anemia (FA), a syndrome characterized by short stature, multi-organ malformations, neurodevelopmental disorders, and cancer susceptibility." (PMID 35563100, 2022). "In cells lacking HR, such as BRCA1/2 deficient cancer cells, TMEJ serves as an essential backup mechanism that still allows resected DSBs to be repaired through the activity of PARP1, DNA ligase III and Polθ (encoded by POLQ)." (PMID 35567571, 2022). "Moreover, a high BRCA1 expression level predicts the poor efficacy of cisplatin-based neoadjuvant chemotherapy in cancer patients." (PMID 35541909, 2022). "Although more cancer-risk genes were considered and their cohort was not limited to BC, 74.5% (287 of 385) were also carriers of variants in BRCA1 or BRCA2 genes." (PMID 36003761, 2022). "Eight genes satisfied both criteria, including BRCA1/2 and a known cancer gene PBX1." (PMID 35625955, 2022).